NR1I2 (nuclear receptor subfamily 1 group I member 2)
Diseases named in the same sentence as NR1I2 in open-access papers:
NR1I2 is named in the same sentence as 182 diseases in open-access papers, as found by Europe PMC text mining. Sharing a sentence is not in itself a finding about the gene and the disease. The quoted sentences say what the papers report.
hepatoma (56 papers, 2008 to 2025). "The TCGA hepatocellular carcinoma cohort was used for internal and external validation and further screening to derive the three core genetic markers, including NR1I2, CDK1, and CHEK1." (PMID 38842135, 2024). "Among the 14 intersecting genes, lasso regression was used to screen for genes with higher prognostic correlation with hepatocellular carcinoma, and a crossover test was performed to screen for three genes with higher prognostic correlation with patients—NR1I2, CDK1, and CHEK1." (PMID 38842135, 2024). "NR1I2, a xenobiotic-sensing nuclear receptor, halts liver cancer progression by inhibiting EMT in hepatocellular carcinoma." (PMID 40108724, 2025). "NR1I2, ESR1, ALPL, MME, IGF1, NR3C2 and PTGS2 were differentially low expressed in hepatocellular carcinoma tissues." (PMID 38842135, 2024).
Hepatic steatosis (49 papers, 2012 to 2025). Steatosis is a term used to denote lipid accumulation within hepatocytes. "PXR knockout (Nr1i2-/-) mice gain less weight on a high-fat diet than wild-type mice and also display decreased liver steatosis and hepatic triglyeride levels." (PMID 30014852, 2018). "In mouse models on a HFD, NDL PCBs, e.g. Aroclor 1260, increased diet-induced hepatic steatosis, inflammation and fibrosis by affecting pathways regulated by epidermal growth factor receptor, constitutive androstane receptor (CAR, Nr1i3) and Pregnane X receptor (PXR, Nr1i2)." (PMID 34548932, 2021).
colon carcinoma (46 papers, 2009 to 2024). "Interestingly, in a cohort of 109 patients with colon cancer, the “inflammatory” variant NR1I2 rs10934498 (G > A) was identified, from a panel of NR1I2 variants, as one of the main determinants of Irinotecan pharmacokinetics." (PMID 33339226, 2020). "NR1I2 is involved in xenobiotic metabolism and expressed in colon cancer SCs." (PMID 30308036, 2018).
breast carcinoma (36 papers, 2008 to 2025). "The TCGA data on the expression of the NR1I2 transcript in the PAM50 breast cancer subtypes are only partially in line with the reported inverse relationship between NR1I2-mRNA expression and ER-positivity." (PMID 26894976, 2016). "SNPs NR1I2 rs3732360 (C > T, C > G), rs1054190 (C > T) and rs1054191 (G > A) are described to be linked with change in doxorubicin pharmacokinetics via altering the miRNA mediated post-transcriptional regulation of PXR in Asian (Indian) breast cancer patients." (PMID 34439808, 2021). "NR1I2 plays a role in breast-cancer cell resistance to anti-tumor agents." (PMID 26894976, 2016). "The group of NRs endowed with potential oncogenic properties in breast-cancer is smaller and consists of the Lipid-Sensors, NR1C2 and NR1I2, the Enigmatic-Orphans, NR1F3, NR3B1 and NR5A2, as well as the Orphan-Receptors, NR2E1, NR2E3 and NR6A1." (PMID 26894976, 2016). "NR1I2 represents a negative prognostic marker in breast-cancer, as NR1I2-protein levels correlate with labeling-index, histologic-grade and lymph-node-status." (PMID 26894976, 2016).
Obesity (34 papers, 2011 to 2025). Accumulation of substantial excess body fat. "The first neighbors of NR1I2 (target of Paxlovid) are linked with colorectal carcinoma, obesity, Fanconi renotubular syndrome with maturity-onset diabetes of the young, thrombocytopenia, and cardiomyopathy." (PMID 37368467, 2023). "Inhibitors which target Slc13a1 and agonists which target Nr1i2 or Ago2 are predicted to have a similar BL6-specific protective effect against diet-induced obesity." (PMID 37871105, 2023). "Although NR1I2 and NR1I3 are xenobiotic receptors investigated in cancer, drug interaction, obesity, and metabolic diseases, in the present study we infer a potential connectivity with many of the MRDT chemicals." (PMID 26662846, 2016).
atherosclerosis (18 papers, 2015 to 2025). A disease characterized by the build-up of fatty material and calcium deposition in the arterial wall resulting in partial or complete occlusion of the arterial lumen. "In addition, genes predicted to be targeted by the miR-17-5p, not previously associated with atherosclerosis, include ARID4B, E2F, GATA1, MEF2D, NR1I2, PURA, and RBL2." (PMID 36859458, 2023).
Insulin resistance (12 papers, 2012 to 2025). Increased resistance towards insulin, that is, diminished effectiveness of insulin in reducing blood glucose levels. "Ablation of Nr1i2 in the whole-body could protect mice from hyperglycemia and insulin resistance and showed improvement of metabolic functions and insulin sensitivity in T2D." (PMID 31579613, 2019). "Also, the transgenic activation of Nr1i2 exacerbated insulin resistance and glucose intolerance in mice." (PMID 31579613, 2019).
diabetes (11 papers, 2017 to 2025). "The first neighbors of NR1I2′s targets are also associated with cancer, leukemia, and thrombocythemia, such as the first neighbors of Sartans’ targets if used as anti-COVID-19 medications, but they are also linked with diabetes." (PMID 37368467, 2023).
dyslipidemia (11 papers, 2014 to 2026). "In addition, recent evidence also show that PXR/NR1I2 is implicated in metabolic syndrome (MetSynd)." (PMID 24498169, 2014).
tuberculosis (9 papers, 2019 to 2025). A chronic, recurrent infection caused by the bacterium Mycobacterium tuberculosis. "In Chinese Han tuberculosis patients who received anti-tuberculosis treatment, with NR1I2 rs7643645 (A > G) were associated with increased risk of anti-tuberculosis drug-induced hepatotoxicity (ATDH) (GG genotype), while carriers of the NR1I2 rs2276707 (C > T) were linked with reduced risk of ATDH." (PMID 34439808, 2021).
injury (7 papers, 2015 to 2024). Damage inflicted on the body as the direct or indirect result of an external force, with or without disruption of structural continuity. "We found that isopimpinellin could directly engage with targets such as NR1I2 and CYP3A4, which are central to the body’s response to oxidative liver injury." (PMID 38666923, 2024).
lung carcinoma (7 papers, 2014 to 2025). "Interestingly, reduced expression of NR1I2 has also been shown to increase the risk of lung cancer, consistent with an important role for this TF in the normal expression of ERCC1." (PMID 28100260, 2017). "The pattern ‘CEGCKGFF’ appeared in 10% of lung cancer cases, specifically in the proteins RARB and VDR, and was also found in NR1I2 and PPARG within the treatment dataset." (PMID 40334012, 2025).
gastric cancer (6 papers, 2015 to 2026). A primary or metastatic malignant neoplasm involving the stomach. "NR1I2 downregulation has been used in constructing a prognostic 9-genes expression signature of gastric cancer." (PMID 31277598, 2019). "In this study, it is the first time to identify NR1I2 and LGALSL associated with gastric cancer as negative impact factors influencing the prognosis of this cancer." (PMID 29088749, 2017).
Hyperglycemia (6 papers, 2014 to 2024). An increased concentration of glucose in the blood. "Based on previous studies, we found the dysregulations of Plin2, Alox15, Nr1i2, and Nr1d1 genes related to lipid metabolism might implicate to the disorders of the hypothalamus in the diabetic GK rats and contribute to the hyperglycemia in them." (PMID 31579613, 2019).
COVID-19 (5 papers, 2022 to 2023). A disease caused by infection with severe acute respiratory syndrome coronavirus 2. "The calculation of the node degree of the first neighbors of Sartans’ two receptors, AT1R and ACE2 (when repurposed for COVID-19), as well as Paxlovid’s receptor (NR1I2), was performed." (PMID 37368467, 2023).
Non-alcoholic fatty liver disease (4 papers, 2020 to 2024). "Again, two NR1I2 gene SNPs that were beyond the scope of our study, namely rs7643645 and rs2461823, are believed to affect HNF binding sites and modulate the risk of anti-TB treatment-related hepatotoxicity and severity of non-alcoholic fatty liver disease." (PMID 38543282, 2024).
primary sclerosing cholangitis (3 papers, 2011 to 2017). "In a Scandinavian study, the prognostic role of the NR1I2 gene variants were examined in primary sclerosing cholangitis; none of the NR1I2 variants were a predisposing factor to the disease, but patients with the rs3814058 homozygous variant genotype had a lower median survival." (PMID 27566582, 2017).
AIDS (2 papers, 2012 to 2017). A syndrome resulting from the acquired deficiency of cellular immunity caused by the human immunodeficiency virus (HIV). "Association of NR1I2 gene polymorphisms and time of progression to AIDS - Table II shows the comparison of NR1I2 SNPs among rapid, typical, and slow progressors." (PMID 28327790, 2017). "On the other hand, the NR1I2 rs3732356G allele frequency was higher among HIV/AIDS patients (48%) compared to healthy subjects (22%)." (PMID 23173844, 2012). "This is the first time an association between NR1I2 polymorphism and time of progression to AIDS is reported and supports an apparent relationship between the gene in the immune response and identifies another genetic factor influencing AIDS progression." (PMID 28327790, 2017). "This study evaluated the possible influence of four common SNPs from NR1I2 gene in the time of progression to AIDS." (PMID 28327790, 2017). "The genotype frequencies between the healthy subjects and HIV/AIDS patients differed significantly for the NR1I2 rs6785049G>A and NR1I2 rs3732356T>G SNPs (P=0.002 and 0.031, respectively)." (PMID 23173844, 2012). "This study aimed to further contribute to the genetic characterization of African populations by genotyping NR1I2 and NR1I3 and evaluating the effects of their variants on the response to efavirenz treatment in HIV/AIDS Bantu-speaking South African patients." (PMID 23173844, 2012). "Targeted sequencing of the DBDs in NR1I2 [GenBank: AF364606] and NR1I3 [GenBank: BC069626.1] in 32 HIV/AIDS patients identified a total of 13 genetic variants." (PMID 23173844, 2012). "However, the NR1I2 rs3732356T>G (P=0.020) genotype frequencies deviated from HWE in the HIV/AIDS patients." (PMID 23173844, 2012). "By observation, the NR1I2 T-G-G haplotype (with respect to rs2472677-rs3732356-rs6785049), which occurs in about 3% of the HIV/AIDS patients, was associated with efavirenz levels greater than 4 μg/mL, and this may influence treatment regimen change." (PMID 23173844, 2012). "This study investigated variation in NR1I2 and NR1I3 and its effect on plasma efavirenz levels in HIV/AIDS patients." (PMID 23173844, 2012). "The distribution of NR1I2 rs3732356T>G and NR1I2 rs6785049G>A genotypes were significantly different between the healthy subjects and HIV/AIDS patients (P=0.031 and 0.002, respectively)." (PMID 23173844, 2012). "The haplotype frequencies in NR1I2 were significantly different between the healthy subjects and HIV/AIDS patients (P=0.015)." (PMID 23173844, 2012). "The NR1I2 (PXR) gene, a ligand-activated transcription factor, regulates the transcription immune pathway genes and can therefore be targets of viral replication mechanisms influencing time of progression to AIDS." (PMID 28327790, 2017). "The difference in genotype frequencies for the NR1I2 rs3732356T>G SNP between the healthy subjects and HIV/AIDS patients may be explained by the deviation from HWE in the HIV/AIDS patients (P=0.020)." (PMID 23173844, 2012).
Cognitive impairment (2 papers, 2022 to 2024). Abnormal cognition is characterized by deficits in thinking, reasoning, or remembering. "Previous studies suggest that NR1I2 may regulate bile acid metabolism involved in promoting the progression of cognitive impairment." (PMID 37008043, 2022).
insomnia (2 papers, 2019 to 2023). A sleep disorder characterized by difficulty in falling asleep and/or remaining asleep. "It was noted that the target of coumestrol, NR1I2, is also insomnia-associated with the corresponding gene." (PMID 37573423, 2023).
Thrombocytopenia (2 papers, 2021 to 2023). A reduction in the number of circulating thrombocytes. "This study also showed that carriers of two copies of the ATG haplotypes of NR1I2 rs1523130 (T > A, T > C, T > G), NR1I2 rs1523127 (T > G) and NR1I2 rs3814055 (C > T) were less sensitive to thrombocytopenia." (PMID 34439808, 2021).
asthma (1 paper, 2023). "The expressions of PTGS1 and CYP3A4 were markedly increased in patients with rhinitis accompanied by asthma, while the expression of NR1I2 decreased synonym." (PMID 37741847, 2023).
brain cancer (1 paper, 2017). A primary or metastatic malignant neoplasm affecting the brain. "At least five of them (ARNT2, NEUROD1, NR1I2, HOXC9, NR4A2) are associated with brain cancer in previous studies." (PMID 29033978, 2017).
cancer (112 papers, 2009 to 2026). A tumor composed of atypical neoplastic, often pleomorphic cells that invade other tissues. "All these targets showed relationship with cancer like Pregnane X receptor (PXR), or NR1I2, is a transcription factor that controls genes related to pharmacokinetics, chemotherapy resistance, and the advancement of cancer." (PMID 39786519, 2025). "It is reported that the expression of NR1I2 was often related to chemoresistance in various cancer cells including HCC." (PMID 34257549, 2021). "Across 5 cancer types, 109 patients who received paclitaxel exhibited activation of NR1I2, many with concurrent activation of CYP2C8 or CYP3A4 – known members of paclitaxel’s metabolic pathway." (PMID 29783934, 2018). "Up to now numerous SNPs have been reported in the NR1I2 gene, some of which may have an impact on the course of cancer treatment." (PMID 34439808, 2021). "NR1I2 plays an integral role in xenobiotic and endobiotic metabolism, glucocorticoid and mineralocorticoid homeostasis, vitamin metabolism, and hepatic gluconeogenesis, and was shown to promote tumor growth and chemo-resistance in major cancer types." (PMID 31851620, 2019). "In summary, 15 polymorphisms were found to be associated with variations in chemotherapy clinical outcome or toxicity in cancers such as breast, gastrointestinal and renal, all of them located in non-translated regions of the NR1I2 gene." (PMID 34439808, 2021).
tumor (79 papers, 2008 to 2025). "To test this hypothesis, we analyzed whether gene expression of ALDH1A1 is positively associated with gene expression of NR1I2 in two independent CRC cohorts containing primary tumor samples versus two cohorts containing metastatic tissue." (PMID 30308036, 2018). "The results revealed that PHGDH and NR1I2 genes exhibited low expression in HCC tumor tissues (P-value < 0.001) while APOC2 genes were highly expressed in HCC tumor tissues (P-value < 0.01)." (PMID 37008043, 2022). "These Nuclear-Receptors represent candidates with potential oncogenic properties, including NR1I2, contributed to the development of therapeutic strategies for increasing their expression or activating them in tumor cells." (PMID 29088749, 2017). "On the other hand, we cannot exclude that the observed impact of the NR1I2 rs1054190-TT genotype on OS could also be due to intrinsic differential tumor aggressiveness related to the patient genetic background." (PMID 31850208, 2019). "Here, we show that the nuclear receptor Pregnane X Receptor (PXR, NR1I2), behaves as a key driver of CSC-mediated tumor recurrence." (PMID 27448961, 2016). "MiR-148a-3p, down-regulated in GC, was shown to influence tumor cell growth, migration, adhesion, invasion and angiogenesis in GC by targeting CDKN1B (p27), NR1I2 (PAR2) and CCKBR genes." (PMID 26172537, 2015).
metabolic disease (20 papers, 2013 to 2025). A congenital disorder (due to inherited enzyme abnormality) or acquired (due to failure of a metabolically important organ) disorder resulting from an abnormal metabolic process. "As a xenobiotic-sensing nuclear receptor, NR1I2/PXR activation was able to alter energy utilization and lipid allocation, which eventually leads to metabolic disorders." (PMID 34201304, 2021).
hematological malignancies (1 paper, 2021). "It has also been reported that the Cssmin of voriconazole, given to patients with hematological malignancies, is affected significantly by SNPs NR1I2 rs2461817 (A > C), rs7643645 (A > G), rs3732359 (G > A), rs3814057 (A > C) and rs6785049 (G > A)." (PMID 34439808, 2021).
peripheral neuropathy (1 paper, 2021). A disorder affecting the peripheral nervous system. "NR1I2 63396TT polymorphisms have been reported to be a risk factor for peripheral neuropathy in patients co-infected with human immunodeficiency virus and Mycobacterium tuberculosis." (PMID 33886687, 2021).
NR1I2 also shares sentences with these, for which no sentence is quoted: cholestasis (43 papers); colitis (42); inflammatory bowel disease (33); steatosis (26); colorectal cancer (24); liver disease (21); prostate carcinoma (17); liver cancer (14); ovarian carcinoma (14); Hypercholesterolemia (13); Cholestatic liver disease (12); colon adenocarcinoma (11); infection (11); type 2 diabetes (10); endometrial cancer (9); Crohn disease (6); Hypertension (6); intrahepatic cholestasis (6); liver fibrosis (6); osteosarcoma (6); acute kidney injury (5); Cirrhosis (5); esophageal adenocarcinoma (5); hyperlipidemia (5); infertile (5); Osteopenia (5); adenocarcinoma (4); cardiovascular diseases (4); kidney diseases (4); osteomalacia (4).
A further 124 diseases each share a sentence with NR1I2 in 4 papers or fewer.